ALCAM (activated leukocyte cell adhesion molecule)
Diseases named in the same sentence as ALCAM in open-access papers (continued):
Sharing a sentence is not in itself a finding about the gene and the disease.
squamous cell carcinoma (5 papers, 2018 to 2025). A carcinoma arising from squamous epithelial cells. "Overall, it appears in squamous cell cancers, to the least in the head, neck, and pharynx tissues, high levels of ALCAM indicate a poor outcome of the patients." (PMID 34680335, 2021). "The long arm of chromosome 3, which presents the ALCAM gene, is a classically amplified genomic region in squamous carcinomas, particularly in esophageal squamous cell carcinoma and HNSCC." (PMID 32085563, 2020). "Additionally, 14-3-3ζ and 14-3-3σ have also been identified as interacting partner proteins for ALCAM in oral SCC (squamous cell carcinoma) cells." (PMID 34680335, 2021). "(A) Circle plots showing the interacting networks between epithelial cell sub-clusters and T cell sub-clusters via the pathway of ALCAM by comparing adenocarcinoma (ADC) and squamous cell carcinoma (SCC)." (PMID 40066698, 2025).
Autoimmunity (4 papers, 2010 to 2024). The occurrence of an immune reaction against the organism's own cells or tissues. "Importantly, the ALCAM/CD6 co-stimulatory pathway has been implicated in collagen-induced arthritis and other models of autoimmunity, and phase 1 clinical trials with anti-CD6 monoclonal antibody therapy in RA patients produced encouraging results." (PMID 37691918, 2023).
brain tumor (4 papers, 2020 to 2023). "ALCAM (also known as CD166-antigen) has been reported to play a major role in infiltration of brain tumors by T-cells and is very relevant to the BBB field." (PMID 36108060, 2022). "Other works by Münsterberg and colleagues have shown that, compared with primary NSCLC, metastatic brain tumours and metastatic lymph nodes had a marked increase in ALCAM staining." (PMID 34680335, 2021). "The expression and function of ALCAM in medulloblastoma (MB), a pediatric brain tumor with highly advanced molecular genetics, remains unclear." (PMID 33270750, 2020).
cervical carcinoma (4 papers, 2012 to 2025). A carcinoma arising from either the exocervical squamous epithelium or the endocervical glandular epithelium. "have demonstrated that overexpression of ALCAM in cervical cancer tissue is associated with increased sensitivity to chemotherapy and radiotherapy." (PMID 39944833, 2025). "In summary we hypothesize, that ALCAM expression in cervical carcinoma might be associated with improved chemoradiation response." (PMID 22475274, 2012). "In this study, ALCAM expression was analysed by immunohistochemistry (IHC) in tissue samples of 233 patients with cervical cancer, among them 178 with complete follow-up information." (PMID 22475274, 2012). "ALCAM-positive and ALCAM-negative cervical carcinomas were first compared regarding their clinicopathological markers." (PMID 22475274, 2012). "ALCAM overexpression was detected (immunoreactive score (IRS) 2-12) in 58.4% of the cervical cancer samples." (PMID 22475274, 2012). "In this hypothesis generating study ALCAM and s-ALCAM expression levels in tumor tissue and sera of cervical carcinoma patients were evaluated for the first time." (PMID 22475274, 2012). "Interestingly, in most cervical carcinomas which exhibit moderate ALCAM staining levels, ALCAM reactivity seemed to be more accentuated at the invasion front." (PMID 22475274, 2012). "Yet, the low s-ALCAM levels in our cervical cancer cohort and the lack of association of s-ALCAM values with ALCAM immunostaining in cancer tissue or patients' outcome suggests that s-ALCAM is not an acceptable serum biomarker in this tumor type." (PMID 22475274, 2012). "The data of our retrospective study suggest that the prognostic value of ALCAM expression in cervical carcinoma might be therapy-dependent, and that ALCAM might function as a predictive marker for the response to chemoradiation." (PMID 22475274, 2012). "In addition, we examined the prognostic and predictive impact of ALCAM expression in cervical cancer and s-ALCAM expression in sera of a subset of patients." (PMID 22475274, 2012). "We could demonstrate that ALCAM expression in cervical cancer could function as a marker for improved outcome in patients treated with radiotherapy or chemoradiotherapy." (PMID 22475274, 2012). "The results of our present study suggest that the consequences of high ALCAM expression might be similar in cervical cancer cells." (PMID 22475274, 2012). "In this hypothesis generating study we analysed ALCAM expression in cervical cancer tissue and its correlation with clinico-pathological tumor characteristics." (PMID 22475274, 2012). "However, the heterogeneity in this first, hypothesis-generating study on ALCAM expression in cervical cancer led to interesting data which suggest that the impact of ALCAM overexpression might be treatment-dependent." (PMID 22475274, 2012). "No data is available for the role of ALCAM or s-ALCAM in cervical cancer so far." (PMID 22475274, 2012).
endometrial carcinoma (4 papers, 2011 to 2021). A malignant tumor arising from the epithelium that lines the cavity of the uterine body. "The study has shown that ALCAM positivity and shorter recurrence-free survival are particularly prevalent in the early stage of endometrial cancers by acting as an independent prognostic indicator." (PMID 34680335, 2021). "Of the endometroid endometrial cancers, over three-quarters of tumours stained positive for ALCAM, mostly membranous and cytoplasmic in location, and the positivity was linked to a shorter recurrence-free survival." (PMID 34680335, 2021). "ALCAM can promote cell migration, invasion, and metastasis in endometrial carcinoma, and is the marker of recurrence in early-stage endometrioid endometrial cancer." (PMID 29375378, 2017). "Soluble ALCAM has also been detected in the uterine aspirates of patients with endometrial cancers." (PMID 34680335, 2021). "The down-regulation of ALCAM in our series of USC samples reinforces its potential role as a molecular predictor of invasiveness and poor outcome in endometrial cancer patients." (PMID 21448288, 2011). "The same authors subsequently reported that most of the ALCAM protein stained in endometrial cancers was on membranes (67.4% positive and 32.6% negative)." (PMID 34680335, 2021).
Ewing sarcoma (4 papers, 2012 to 2025). A small round cell tumor that lacks morphologic, immunohistochemical, and electron microscopic evidence of neuroectodermal differentiation. "To determine if ALCAM palmitoylation plays a role in Ewing sarcoma migration, we treated our Ewing sarcoma cells with palmostatin B, a small molecule inhibitor of APT1, and evaluated the cells’ ability to migrate." (PMID 41301074, 2025). "Inhibition of Wnt signaling, FAK phosphorylation, or ALCAM palmitoylation can each diminish Ewing sarcoma cell migration." (PMID 41301074, 2025). "We demonstrate changes to FAK phosphorylation, cross-linking of filamentous actin by vinculin to ALCAM, and alterations in post-translational modifications of ALCAM, which all affect Ewing sarcoma cell migration." (PMID 41301074, 2025). "Cell adhesion molecule MCAM has been shown to play a role in Ewing sarcoma migration and metastasis, while ALCAM is expressed in more than 70% of pediatric sarcomas, leading us to focus on cell adhesion membrane family members." (PMID 41301074, 2025). "In a cohort of 98 Ewing sarcomas, ALCAM (mostly membranous) was found in the majority of the tumours, and patients with high levels of ALCAM had favourably MFS (metastasis-free survival)." (PMID 34680335, 2021). "Likewise, expression of an ALCAM transcription suppressor, together with a reduced ALCAM level in Ewing sarcoma, results in patients with marked decreases in metastasis-free survival." (PMID 34680335, 2021). "In addition, when A4573 cells were treated with palmostatin B, immunofluorescence analysis revealed that ALCAM became more diffuse and punctate throughout the cells with a visible decrease in vinculin, suggesting that these proteins all interact in Ewing sarcoma cells." (PMID 41301074, 2025). "Changes in N-glycosylation of ALCAM in Wnt5a knock-out cells may suggest that post-translational modifications might affect Ewing sarcoma cell migration as the Wnt5a knock-out clones do not migrate well." (PMID 41301074, 2025).
nasopharyngeal carcinoma (4 papers, 2017 to 2024). A carcinoma arising from the nasopharyngeal epithelium. "ALCAM can also enhance the cancer stem cell-like (CSC) phenotype of nasopharyngeal carcinoma by activating the EGFR/ERK1/2 signaling pathway, and ALCAM downregulation decreases tumor sphere formation, thus inhibiting CSC-like characteristics and weakening tumorigenesis capacity in vivo." (PMID 37701037, 2023). "Knock-down of activated leukocyte cell adhesion molecule (ALCAM) results in a reduction in EGFR phosphorylation and MAPK activation in nasopharyngeal carcinoma CNE-2R cells in the absence of EGF, suggesting that ALCAM also maintains the ligand-independent activity of EGFR." (PMID 39594667, 2024).
triple-negative breast carcinoma (4 papers, 2020 to 2023). An invasive breast carcinoma which is negative for expression of estrogen receptor (ER), progesterone receptor (PR), and human epidermal growth factor receptor 2 (HER2). "On the other hand, the correlation of ALCAM expression with AR gene expression score seems to be in line with current observations made in triple negative breast cancer where high ALCAM tissue protein expressions were shown to be associated with higher AR protein expression." (PMID 35689436, 2022). "Previous research showed that miR-483-5p had a prometastatic function that downregulated tumor suppressors RhoGDI1 and ALCAM (activated leukocyte cell adhesion molecule), inhibited miR-483-5p, and could also impede tumor proliferation in triple-negative breast cancer." (PMID 37298699, 2023).
asthma (3 papers, 2019 to 2023). "Similarly to CD6-deficient mice, ALCAM-deficient mice were found to develop a reduced T cell response in vivo, as recently demonstrated in mouse models of asthma, atopic dermatitis, and food allergies." (PMID 37514028, 2023). "Further studies are needed to assess the suitability of anti-ALCAM mAbs upon delivery by inhalation, i.e., the most suitable route of topical administration for therapeutic proteins in human asthma." (PMID 37514028, 2023). "For instance, intranasal delivery of rabbit polyclonal anti-ALCAM antibodies significantly reduced the inflammatory response in a murine asthma model." (PMID 37514028, 2023). "At this point, our study confirms ALCAM as a therapeutic target for asthma and demonstrates the in vivo activity of both IF8-Fc and scFv V2D7 upon intranasal administration." (PMID 37514028, 2023). "This indicates that, as previously suggested, the reduced T cell activation and proliferation is the critical mechanism by which ALCAM blockade reduces inflammatory symptoms in OVA-induced asthma." (PMID 37514028, 2023). "Treatment with polyclonal goat anti-mouse ALCAM antibody was recently shown to reduce allergic symptoms in a murine asthma model, but polyclonal antibodies from other species are not suited for long-term therapies due to immunogenicity." (PMID 31031759, 2019). "Specifically, in an OVA-induced murine asthma model, intranasal treatment with a polyclonal rabbit anti-ALCAM antibody at the time of OVA challenge reduced allergic symptoms, such as the leukocyte count and Th2 cytokine (i.e., IL-4, IL-5, and IL-13) levels in BAL fluid." (PMID 37514028, 2023). "Furthermore, intranasal delivery of anti-ALCAM fragments reduced leukocyte infiltration in a mouse model of asthma, confirming ALCAM as a target for topical application in the lungs." (PMID 37514028, 2023). "Activated leukocyte cell adhesion molecule (ALCAM) is a cell adhesion molecule that supports T cell activation, leukocyte migration, and (lymph)angiogenesis and has been shown to contribute to the pathology of various immune-mediated disorders, including asthma and corneal graft rejection." (PMID 37514028, 2023). "Taken together, these findings confirm the in vivo therapeutic activity of the ALCAM-blocking parental antibody construct IF8-Fc and the affinity-matured and stability-optimized clone V2D7 in scFv format in a mouse model of asthma." (PMID 37514028, 2023).
atopic dermatitis (3 papers, 2022 to 2023). "Atopic dermatitis (AD) is reported to be correlated with AD‐HIES (job's syndrome), IPEX, Netherton syndrome, PGM3 deficiency, DOCK8 deficiency, STAT3 GOF, Omenn syndrome, activated leukocyte cell adhesion molecule (ALCAM), and hypereosinophilia." (PMID 37102642, 2023).
diabetes (3 papers, 2019 to 2024). "In type 2 diabetic nephropathy, serum ALCAM level and ALCAM expression in the glomeruli were significantly increased, suggesting ALCAM as a potential mediator in the late complications of diabetes in the kidney." (PMID 32460901, 2020). "Currently, ALCAM was identified as a potential mediator in the late complications of diabetes in the kidney." (PMID 31467530, 2019).
diabetic nephropathy (3 papers, 2022 to 2024). "In diabetic nephropathy, serum concentrations of ALCAM as well as its expression in kidney tissue were significantly elevated and upregulated in glomeruli and tubules." (PMID 35720325, 2022). "Interestingly, in diabetic nephropathy, serum concentrations of ALCAM have been shown to be elevated and inversely correlated with renal function, while ALCAM expression was upregulated both in glomeruli and tubules, mainly in podocytes, though uALCAM was not examined." (PMID 34981775, 2022).
experimental autoimmune encephalomyelitis (3 papers, 2017 to 2021). An autoimmune demyelinating disease of the central nervous system that is produced experimentally in animals by the injection of homogenized brain or spinal cord in Freund's adjuvant. "Additionally, activated leukocyte cell adhesion molecule (ALCAM/CD166), the known ligand for CD6 domain 3, is over-expressed in blood brain barrier cells within the central nervous system of MS patients and in experimental autoimmune encephalomyelitis lesions." (PMID 28672038, 2017).
heart failure (3 papers, 2020 to 2025). Inability of the heart to pump blood at an adequate rate to meet tissue metabolic requirements. "Additionally, patients with elevated ALCAM levels showed a significantly higher prevalence of heart failure history compared to those with low ALCAM levels, suggesting that elevated ALCAM levels in ACS patients with poor prognoses may be linked to inflammatory response." (PMID 40089108, 2025).
mesothelioma (3 papers, 2016 to 2023). A usually malignant and aggressive neoplasm of the mesothelium which is often associated with exposure to asbestos. "In addition, soluble ALCAM was found to be able to inhibit ALCAM-mediated cell adhesion and migration of mesothelioma cells." (PMID 36614319, 2023). "However, patients with membranous ALCAM-positive mesotheliomas had a marked shorter survival compared with those with either negative ALCAM or cytoplasmic ALCAM, arguing membranous ALCAM as an independent prognostic indicator in this tumour type." (PMID 34680335, 2021).
Obesity (3 papers, 2016 to 2020). Accumulation of substantial excess body fat. "Five of the twenty-one obesity-dependent DEGs are associated with obesity and insulin resistance (MPHOSPH9, BRCA1, ASP, ALCAM, GP2)." (PMID 30305020, 2018). "Also, 4 of these DEGs have a known-role in placenta development and function (ALCAM, BRCA1 GP2, GSTA4) and 5 are associated with obesity and insulin resistance (MPHOSPH9, BRCA1, ASP, ALCAM, GP2)." (PMID 30305020, 2018). "Whether the expression of the full receptor ALCAM in endothelial cells or circulating cells such as macrophages is involved in the molecular mechanism of obesity-induced insulin resistance requires further investigation." (PMID 27737658, 2016). "Further studies are required to determine whether the scavenging of ALCAM or RAGE ligands by sALCAM is functionally related to the inhibition of detrimental ALCAM signalling in obesity." (PMID 27737658, 2016).
oral squamous cell carcinoma (3 papers, 2013 to 2025). "We showed ALCAM overexpression in early oral lesions and its cytoplasmic accumulation in oral squamous cell carcinoma (OSCC) to be a predictor of disease progression and poor prognosis." (PMID 23840677, 2013).
ovarian tumors (3 papers, 2015 to 2023). "Hence, any event that perturbs the connection between ALCAM and its ligands brings about repercussions on the motility of ovarian tumor cells." (PMID 26339605, 2015). "For ovarian tumors, there is little specific information that ascertains the involvement of MCAM, L1CAM (CD171), EpCAM, IgLON, and ALCAM/CD166 (Activated Leukocyte Cell Adhesion Molecule)." (PMID 26339605, 2015).
Sjogren syndrome (3 papers, 2017 to 2024). An autoimmune disorder in which immune cells attack and destroy the glands that produce tears and saliva. "In Sjögren's syndrome, ALCAM is overexpressed in the salivary glands of these patients and the use of itolizumab as therapeutic option has been proposed for clinical trials." (PMID 36275816, 2022).
thyroid cancer (3 papers, 2011 to 2021). "Additionally, in thyroid cancer, increased serum levels of ALCAM have been seen in patients with aggressive tumours and with lymph node metastases." (PMID 34680335, 2021). "We also specifically investigated whether ADAM17/TACE was responsible for shedding of ALCAM in thyroid cancer cells and we found the existence of a novel 60-kDa soluble form of ALCAM." (PMID 21364949, 2011). "We show that ALCAM expression is also modulated in thyroid cancer." (PMID 21364949, 2011). "Our data indicate that activated EGFR also cooperates in thyroid cancer cell lines with the ADAM17/TACE sheddase in promoting ALCAM shedding and soluble ALCAM release." (PMID 21364949, 2011).